IL6 (interleukin 6)
Diseases named in the same sentence as IL6 in open-access papers (continued):
Sharing a sentence is not in itself a finding about the gene and the disease.
infection (continued). "IL-1β, IL-6 and IL-8 are commonly upregulated by infection and induce prostaglandin (PG)E2 and PGF2α production to stimulate myometrial contractility and PTB." (PMID 34394055, 2021). "Conversely, IL-6 expression in the serum is markedly increased in LTβR−/− mice compared to WT mice throughout the infection." (PMID 33753412, 2021). "Retrospective analysis of human samples after an Italian CHIKV outbreak revealed an increase in IL-6 during the acute phase of infection, and low levels of IL-1β, TNF-α, IL-12, IL-10, IFN-γ, and IL-5 that increased as disease progressed to the chronic state." (PMID 34106915, 2021). "While there were still no off-target effects as evidenced by testing responses to flagellin, both inhibitors decreased IL-6 and TNFα levels in response to infection and control agonists." (PMID 34280250, 2021). "Evidently, such a profound dysregulation of IL-6 production in patients with HIV/TB is explained by the synergistic effect of both infections and contributes to the development of both HIV and TB pathology." (PMID 34835417, 2021). "IL-6 is the foremost cytokine in acute phase inflammation, an innate immune response elicited by infection." (PMID 34220807, 2021). "The model was based on experimental data obtained from the literature as well as our predictions, which further depicted the role of TLR2 and IL6 signaling pathways during the early stage of infection." (PMID 35011356, 2021). "The exosomes secreted by microglia during TMEV infection also induced the expression of pro-inflammatory cytokines, IL-6, IL-12, and TNFα, and chemokines, CCL2, in bystander uninfected microglia." (PMID 34485270, 2021). "The avian H7N9 (H7/SH2/13) also can infect human neurons and astrocytes cell lines, and thus the infection results in the increase of IL-6, IL-8, TNF-α, IFN-β, and CCL2." (PMID 33917837, 2021). "Five days post infection (dpi), the mice administered the different strains showed increased expression of cytokines Il-6 and Il-1β in mesenteric lymph node (MLN) leukocytes (p < 0.05)." (PMID 34785760, 2021). "Compared to the sham group, the lung tissue of M. tb-infected mice treated with DEM had significantly higher levels of IL-6 at both 4 weeks and 8 weeks post-infection." (PMID 35371562, 2021). "We observed that IFN-β, IL-6 and IL-12 gene expression was higher at day 4 after infection and decreased overtime in both groups of animals." (PMID 35095849, 2021). "4-MTBITC inhibited the expression of genes NF-kB, and IL-6, which control the immune response to infection." (PMID 34447314, 2021). "In contrast, in LTβR−/− mice, IL-6 amounts rose significantly during the course of infection and were significantly higher on days 7 and 10 p.i. than those of WT mice." (PMID 33753412, 2021). "EV-A71 infected cells produce cytokines such as TNF-α, IFN-γ, and IL-6, which play an important role in controlling viral replication and infection at the early stage." (PMID 34493781, 2021). "Because IL-6 influences host defense, blockade of IL-6 signaling silences inflammatory responses, which makes it difficult to assess the severity of infection." (PMID 34253862, 2021). "Infection triggers the release of cytokines such as interleukin 1 (IL-1), tumor necrosis factor α (TNFα), and interleukin 6 (IL-6), which stimulate the hypothalamus-pituitary-adrenal (HPA) axis to increase the cortisol levels." (PMID 34283908, 2021). "IL6, the most commonly secreted cytokine during infection, has the potential to alter the cognitive behavior of the progeny to an extent that there is a negative correlation between maternal IL6 and the memory of young children." (PMID 34858132, 2021). "IL-1β and IL-6 enable transmigration of immunocompetent cells to sites of infection by the increased expression of adhesion factors on the surface of the endothelial cells." (PMID 34694623, 2021). "In this study, elevated CRP which is induced by IL-6, was present after infection with all three strains of B. pseudomallei." (PMID 33571211, 2021).
infection (continued). "Ptpn11 is the gene that encodes for SHP-2 and it was crucial for the induction of interleukin 1b (IL-1b), IL-6 and IL-23 and responses of the Th17 subset of helper T cells in controlling infection." (PMID 34759909, 2021). "In contrast, we noticed an EPs 7630-mediated increase in IL-1β and IL-6 levels early post-infection (8 h), with enhanced IL-6 levels also detectable late after infection (48 h)." (PMID 34759825, 2021). "As expected, the rgH3N2 and rgH3N2 4xM2e groups presented significantly lower amounts of TNF-α, IFN-γ and IL-6 than the naïve group after infection with rgH5N1." (PMID 33603072, 2021). "We observed that genotype IIR infection results in upregulation of the pro-inflammatory cytokines IL-6 and IL-8, especially IL-6 at 15 dpe in rainbow trout." (PMID 35071050, 2021). "The transcripts of proinflammatory cytokines (il-1β, il-6, tnfa) and cox2 were significantly (p < 0.05) upregulated at 24 h post-infection (hpi) in IPNv-infected fish." (PMID 34768822, 2021). "The expression of il-1b, il-6, il-8, and il-10 was increased along with the infection time, where the expression of the four genes was higher at 33°C than at 18°C." (PMID 34566956, 2021). "Following infection, pro-inflammatory cytokines IL-6, interleukin-22 (IL-22) and interleukin-1 (IL-1) produced by cells of the innate immune system, such as natural killer (NK) cells and macrophages, initiate acute phase response in the liver." (PMID 34571900, 2021). "IL-6 and amyloid A staining in baboon livers (B9015, B9313) represented the Rejection and Infection groups." (PMID 34956220, 2021). "Transitionary synthesis of IL-6 results in a rapid contribution to the host defense against infection and injury and simultaneously provides a warning signal by activating a broad spectrum of biological events." (PMID 33409539, 2021). "In this report, we found ORMDL3 knockdown epithelial cells release less IL-6 after HRV16 infection, consistently confirm the results from poly I:C stimulations in ORMDL3 knockdown cells." (PMID 34001091, 2021). "When the general conditions of patients improved, the values of infection biomarkers, especially IL-2R, IL-6 and CRP, significantly decreased." (PMID 33542448, 2021). "TLR4 allows translocation and activation of the transcription factor NF-ĸB, which stimulates synthesis and secretion of cytokines (IL-6, TNFα) at the site of the infection, which will propagate the immune response." (PMID 33801785, 2021). "From the perspective of the innate immune response, IL-6 induces the recruitment of white blood cells and promotes apoptosis of neutrophils, mediating inflammation to control infection." (PMID 34093528, 2021). "Serum levels of acute phase proteins (APP) change during the course of infection, inflammation, tissue injury, neoplastic processes or stress, stimulated by proinflammatory cytokines such as IL-6 or TNF-α52." (PMID 34103567, 2021). "More specifically, IL-6 was increased in TNC−/− mice compared to TNC+/+ mice (P = 0.009) at 6 h after infection." (PMID 34319124, 2021). "TRIF-/- Hoxb8 neutrophils secreted significantly more RANTES, TNF and IL-6 than WT cells upon infection." (PMID 33747981, 2021). "As mentioned, T. gondii infection leads to the suppression of anti-inflammatory IL-6 signals by SOCS3 to control infection." (PMID 33205383, 2021). "During infection and trauma, the secretion of pro-inflammatory cytokines including IL-1, IL-6, and TNF-α, induce the production of C-reactive protein (CRP), procalcitonin (PCT), ferritin, and serum amyloid A (SAA) as common inflammatory mediators." (PMID 35126355, 2021). "In previous studies with C. albicans, we have observed elevated IL-6 levels in the serum of mice with higher fungal burdens, and our data with Mincle KO mice suggest a similar trend during infection with C. tropicalis." (PMID 33717025, 2021).
infection (continued). "Western blot data depicted increased expression of SOCS1 and SOCS3 protein during infection which further got enhanced in presence of IL6 treatment." (PMID 35011356, 2021). "The 3T6 cells were infected with various MOI, and IL-6 secretion was measured until 7 days post-infection." (PMID 33923020, 2021). "In the rN-BmRON2 and rC-BmRON2 groups, IL-2, IL-4, IL-6 and IL-17a levels peaked on the 21st day after infection, but then decreased rapidly." (PMID 33717108, 2021). "Stimulation with the FimH protein induced a significant increase in IL-8 and IL-6 release at 3 and 5 h after infection." (PMID 34835359, 2021). "In particular for Pt #13, significantly elevated level of baseline IL6 implied the presence of infection right before CART infusion." (PMID 34518515, 2021). "In addition to polyphenols, Interleukin 6 (IL-6) has often been identified as an inflammatory biomarker associated with fatigue, skeletal muscle inflammation, and differentiation of immune response, as well as an inducer of the metabolic acute phase response to infection." (PMID 33540813, 2021). "Interleukin-6 is produced by many different cell types (both in immune and non-immune associated cells), and while it is well known to have a protective role in many infections, these same activities may be the key to the switch from acute to chronic inflammation." (PMID 34295313, 2021). "IL6, acting as a pro-inflammatory mediator, contributes to host defense during infection and tissue injury, but anti-inflammatory properties have also been suggested depending on the presence of other cytokines." (PMID 34200627, 2021). "Despite the differences in the magnitude of induction between each HBEC donor, combined, we observed a consistent trend of proinflammatory cytokine and chemokine (CCL2, CCL20, CXCL6, IL-6 and TNFα) inductions within 24 h post-infection with SARS-CoV-2." (PMID 34452468, 2021). "The increase in the secretion of IL-6 is observed in the course of reactions related to the acute phase of inflammation occurring in the course of trauma, stress, infections, cerebral death, and neoplastic processes." (PMID 34372587, 2021). "Infection during pregnancy activates the mother’s immune system to release proinflammatory cytokines, such as IL-6, TNF-α, and others." (PMID 34768946, 2021). "Results showed that the effects of H9N2 AIV infection and DATS treatment on the expression of TNF-α and IL-6 were most profound at 6 days post infection." (PMID 34412671, 2021). "For having remained below the technique detection limit, we did not interpret the following values: uninfected mice, IL-2, IL-4, IL-10, and IL-17 values of infected mice, as well as IFN-γ, TNF-α, and IL-6 levels at the infection times from 6 to 240 h." (PMID 34660334, 2021). "Three key proteins generally involved in infection and inflammation (IL6 IL18, and IFNG) are the focus of this analysis and are associated with 10 other proteins." (PMID 35145507, 2021). "IL-6 is a multifunctional cytokine with both pro-inflammatory and anti-inflammatory effects produced in response to tissue damage and infections." (PMID 34835417, 2021). "Next, we measured the expression of proinflammatory cytokines/mediators (IL-1β, TNF-α, IL-6 and iNOS) in brain lysates (cortex and hippocampus) and serum at 24 h post-infection by RT-PCR and ELISA, respectively." (PMID 34727939, 2021). "It was proposed that IL-1 and IL-33 generated by keratinocytes in response to infection activate MCs to produce IL-6, which in turn generate HDPs from keratinocytes resulting in the direct bacterial killing." (PMID 34248979, 2021). "The data in this critical study demonstrated that through Notch-1/IL-6 signaling, anti-TNF-α agents decreased ACE2 expression and shedding through TMPRSS2/TACE modulation and increased the susceptibility to infection." (PMID 34025650, 2021). "Interleukin-6 (IL-6) is a pleiotropic proinflammatory cytokine produced by a variety cells in response to infection." (PMID 34708133, 2021).
infection (continued). "The time course RT-qPCR analysis demonstrated a dramatic increase in the expression of the proinflammatory cytokine mRNAs for CXCL-13, IFNγ, and IL-6 with infection." (PMID 34451461, 2021). "Infection with the CFT073 strain under the three infection conditions induced IL-6 release at levels of 1323.58 to 1579.89 pg/mL (at 3 h after infection) and 967.25 to 2170 pg/mL (at 5 h after infection)." (PMID 34835359, 2021). "A total of 11,984 genes were differentially expressed during the late stage of the infection, most notably interferon-gamma, interleukin-6, and immunoglobulin transcripts." (PMID 34578212, 2021). "IL6 appeared as a central node among the added first neighbors, and elevated levels of it are related to infection severity." (PMID 35154611, 2021). "Infection was accompanied by progressive upregulation of proinflammatory cytokines such as IL6, IL1B and TNF, consistent with initiation of an NF-KB-dependent inflammatory response." (PMID 34876592, 2021). "In contrast with these studies, we did not observe significant DCA-inhibiting effects on IL-1β, IL-10 and IL-6 secretion by Stm- or Mtb-infected human macrophages, possibly because infection alone already strongly skewed the cytokine response." (PMID 34552598, 2021). "Liver samples were collected approximately 7 d prior to infection and then on day 10 post-infection and evaluated for gene expression of the inflammatory cytokines IL-6 and TNF-α, and the acute-phase protein haptoglobin." (PMID 34673945, 2021). "The level of IL-6 in the blood has also been shown in literature search and analysis studies to have clinical usefulness in distinguishing people with severe infections." (PMID 34925324, 2021). "IL-6 levels are increased during infection and IL-6 is a significant modulator of the cytokine storm." (PMID 33969006, 2021). "As a proinflammatory cytokine, IL-6 was available in peripheral blood at the early stage of the infection, which then led to the generation of CRP in the liver." (PMID 33575324, 2021). "As there were 7 out of 10 pathways was related to infection or lymphocyte immunity, such as IL-6, IL-8, CXCR2, TGF-β, autophagy, and HIV-1 replication, whereas BMP singling was associated with extracellular interactions." (PMID 35401158, 2021). "IFN‐g, TNF‐a, IL‐6, and IL‐10 were all increased after challenge, but IL‐6 and IL‐10 levels dropped quickly 3 days post‐infection." (PMID 34176237, 2021). "With this in mind the serum IL-6 levels was determined with ELISA in the two independent experimental infections [experiment #1 (SG+/+ n = 6, SG−/− n = 6) and #2 (SG+/+ n = 5, SG−/− n = 11)]." (PMID 34335577, 2021). "Interleukin-6 (IL-6) is a prominent proinflammatory cytokine released during infection or tissue injury that contributes to both innate and adaptive immune responses." (PMID 34253862, 2021). "In cattle, a shift towards Th2 responses highlighted by involvement of Th2 response and IL-4 and IL-6 signalling pathways occurred in the acute phase of infection." (PMID 34616397, 2021). "In the tongue, the infection by S. camelicanis increased the IL-6 expression approximately 48-fold in Al Qassim but only 0.7-fold in Riyadh." (PMID 33409539, 2021). "IL-6 aids short-term protection against infection or damage by alerting the immune system to the source of inflammation." (PMID 34903932, 2021). "The production of PCT during bacterial infection is mediated by tumour necrosis factor-alpha and interleukin 6, which increases during infection." (PMID 34336223, 2021). "IL-6, IL-8, and IL-12 were induced by Phdd infection and were higher in the Sarcodia-Phdd group than the other two groups at 24 h post infection." (PMID 35140710, 2021). "Other researchers have shown that IL-6 levels increase in the milk and blood from lactating cows with a naturally acquired or experimentally induced infection." (PMID 34711282, 2021).
infection (continued). "At the time of initial infection of the CMs, production of IL-6, eotaxin, IL-1RA, I-TAC, and MCP-1 was observed in the infected CMs, and transient increases in the levels were observed." (PMID 34625475, 2021). "Compared to the inflammatory markers used in the clinic routine, we found a positive correlation between IL-6 and the grade of infection." (PMID 34576798, 2021). "Serum proinflammatory cytokines (interleukin-6 [IL-6], IL-1β, gamma interferon, and tumor necrosis factor alpha) and the anti-inflammatory cytokine IL-10 were first detected at 12 h postburn with infection and continued to increase until death." (PMID 34152806, 2021). "Relative quantitative RT-qPCR was used to assess relative gene expression of pro-inflammatory cytokines (IL-6, IL-8, and IL-10) in the ileum of birds following E. coli challenge on 2 days after infection." (PMID 34903932, 2021). "Corroborating its anti-inflammatory action, Quercetin treatment significantly reduced TNF and IL-6 production in human macrophages following infection with P. gingivalis and F. nucleatum." (PMID 34899728, 2021). "To gain insights into the relationship between the stress and inflammation induced by infection viral, we measured the plasma levels of Tnfa, Il-6, Pge2, and cortisol through the ELISA assay." (PMID 34768822, 2021). "In particular, Lf down-regulates the synthesis of IL-6, which is involved in iron homeostasis disorders and leads to intracellular iron overload, favoring viral replication and infection." (PMID 34220505, 2021). "The expression of Ifnb1, Il6, and Ifna4 were increased in BMDMs from Mettl14+/− mice after infection with SeV or treatment with 5′‐pppRNA, compared to that in wild‐type BMDMs from Mettl14+/+ littermates." (PMID 34047074, 2021). "Accordingly, IL-6 levels were highly elevated by infection with SARS-CoV-2 but mitigated to the average cell level after treatment with Poly6 in a dose-dependent manner." (PMID 34202029, 2021). "Modulating the immune response with azithromycin consistently results in decreased production of IL-6 across both infection- and non-infection-driven pathology." (PMID 33643308, 2021). "In the present study, we compared the expression levels of the Th1-type cytokines IL-1β, TNF-α and IL-6 and the Th2-type cytokines IL-4 and IL-10 in susceptible host BALB/c mice and resistant host M. fortis on different days post-infection with S. japonicum." (PMID 34689797, 2021). "Blood IL-6 is an early sensitive marker of neonatal bacterial infection and one of the most studied cytokines in the diagnosis of infection in neonates." (PMID 34708133, 2021). "Yet, both KO’s of TRIF led to a significant reduction in IL-6 as measured at 9 h after infection (top), in agreement with our shRNA-based experiments." (PMID 34280250, 2021). "Recently, palmitoleate was also shown to inhibit TNFα, IL-1β and IL-6 proinflammatory cytokine responses in candida-infection stimulation analysis." (PMID 33886600, 2021). "IL-6 is a cytokine that is produced rapidly and briefly, primarily in response to infection and tissue damage, and thus contributes to host defense." (PMID 34790229, 2021). "The present study demonstrated that neutropenic animals had an increase in the IL-6 production in the spleen and liver, followed by a lower fungal burden in these organs up to 14 days of infection." (PMID 34642440, 2021). "BMDMs from these Ifnar−/− mice also exhibited increased expression of Il1b, Tnf, and Il6 with MHV-A59 infection compared to uninfected Ifnar+/+ controls." (PMID 34479991, 2021). "The magnitude of spleen-tissue interferon (IFN)-α, IFN-β, IFN-γ, interleukin (IL)-1β and IL-6 expression induced by infection with the R543K mutant was significantly lower than those of JXSP2-4, but higher than those of the JXSP-310RdRp-infected ducklings." (PMID 34065634, 2021).